CACNA1C (calcium voltage-gated channel subunit alpha1 C)
Diseases named in the same sentence as CACNA1C in open-access papers (continued):
Sharing a sentence is not in itself a finding about the gene and the disease.
psychiatric disorder (continued). "Overall, these results suggest that genetic variation in CACNA1C may contribute to risk for psychiatric disorders through impacting cognitive flexibility, and that at a molecular level, this may be in part caused by alterations in BDNF expression." (PMID 30304534, 2019). "We then examined methylation in a shortlist of genes that were previously associated with early life stress and psychiatric disorders as well as placental functioning: Ank3, Avp, Avpr1a, Avpr1b, Bdnf, Cacna1c, Cyp11b1, Cyp11b2, Fkbp5, Hsd11b1, Igf2, Morc1, Nr3c1, Oxt, Oxtr, Pclo, Slc6a4." (PMID 30655507, 2019). "The robust association of CACNA1C with multiple psychiatric disorders has led to the investigation of potential endophenotypes and downstream biological mechanisms that may link genetic risk to disease-relevant behavior." (PMID 30304534, 2019). "In addition to ASD, SNPs in CACNA1C gene are linked to psychiatric disorders including schizophrenia and bipolar disorder." (PMID 29934975, 2018). "Interestingly, a number of genome-wide association studies have linked single nucleotide polymorphisms (SNPs) in CACNA1C to several psychiatric disorders, and it has been variously suggested that these SNPs are putative neuropsychiatric risk alleles." (PMID 27957527, 2016). "Recent association studies identified CACNA1C as one of the most promising genetic risk factors for psychiatric disorders and previous evidence suggests that the most replicated risk variant in CACNA1C (rs1006737) is affecting emotion recognition and processing." (PMID 26611642, 2015). "Several studies demonstrated an association between the most replicated CACNA1C risk variant rs1006737 and emotion recognition and processing, suggesting an influence of CACNA1C not only on the risk for psychiatric disorders themselves, but also on intermediate phenotypes underlying them." (PMID 26611642, 2015). "Previous research showed that CACNA1C could cause pathophysiology of psychiatric disease, and CACNA1C has high transcript activity in the prostate stroma." (PMID 26147197, 2015). "The increasing findings in genetic studies indicates that the CACNA1C gene is one of shared susceptibility factors for major psychiatric disorders and may have played an important role in the pathogenesis of these diseases at some level." (PMID 26255836, 2015). "Therefore, CACNA1C plays important roles in the proper function of numerous neurological circuits including hippocampus, amygdala, and mesolimbic reward system, which are strongly implicated in psychiatric disease pathophysiology." (PMID 26204268, 2015). "Our study is the first to provide evidence for an impairing behavioral effect of the CACNA1C risk variant rs1006737 on facial emotion recognition in healthy individuals and adds to the growing number of studies pointing towards CACNA1C as affecting intermediate phenotypes of psychiatric disorders." (PMID 26611642, 2015). "To address the cell type-specific contribution of Cav1.2 to endophenotypes related to psychiatric disorders, we generated mice with a conditional Cacna1c deletion in PV+ neurons (Cav1.2-PV)." (PMID 42009796, 2026). "Thus, the hypercortisolism and GR resistance in Cacna1c+/− rats may represent a model of heightened vulnerability to stress and stress-associated cognitive, behavioural, metabolic, and neuroimmune changes linked to various psychiatric disorders." (PMID 40565009, 2025). "CACNA1C, coding for the α1 subunit of L-type voltage-gated calcium channel (LTCC) Cav1.2, has been associated with multiple psychiatric disorders." (PMID 39370418, 2024). "Accumulating evidence has suggested that miR-137 and its target genes, CACNA1C, and TCF4, are amongst the most robustly implicated genes in psychiatric disorders." (PMID 36193501, 2022). "The cumulative GWAS data strongly suggest a role for common variation in VGCC subunit genes, especially CACNA1C, in the genetic architecture of severe mental illness." (PMID 36154842, 2022).
psychiatric disorder (continued). "Noteworthy, CACNA1C polymorphisms have been consistently associated with BIP and SCZ, among other psychiatric disorders." (PMID 35013130, 2022). "For CACNA1C and TCF4, two genes that have been repeatedly linked to major psychiatric disorders from GWAS and a few rare variant association studies, we studied the role of deep-sequenced rare variation across a spectrum of mental illnesses." (PMID 35590255, 2022). "Among the Ca2+ channels, CACNA1C-encoded CaV1.2, an L-type VDCC, is strongly associated with psychiatric disorders." (PMID 33644051, 2021). "Our library included amplicons spanning across a psychiatric disorder-associated LD interval within the ~330 kb third intron of the gene CACNA1C, which encodes the α1 subunit of the L-type voltage-gated calcium channel CaV1.2." (PMID 34605404, 2021). "While the gene CACNA1C is also the genome-wide significant loci (rs1024582) shared among these five major psychiatric disorders in previous PGC cross-disorder work." (PMID 33371872, 2020). "The CACNA1C is a gene contributes to the etiology of psychiatric disorders and to phenotypes affected by those conditions such as memory and circadian rhythms." (PMID 32316129, 2020). "The discovery that voltage-gated calcium channel genes such as CACNA1C are part of the aetiology of psychiatric disorders has rekindled interest in the therapeutic potential of L-type calcium channel (LTCC) antagonists." (PMID 30755265, 2019). "Similar to CACNA1C, SNPs in CACNB2 have shown strong association with BD and other psychiatric disorders." (PMID 31331039, 2019). "In a large GWAS, two genes encoding the α1 subunit of calcium channel (CACNA1C) and its regulatory β2 subunit (CACNB2) were strongly linked to psychiatric disorders and ASD (Cross‐Disorder Group of the Psychiatric Genomics Consortium, 2013)." (PMID 29934975, 2018). "Our results, overall, provide strong support for a role of CACNA1C regulation in psychiatric disease." (PMID 27276213, 2016). "Our finding that risk-allele carriers are subtly challenged in facial emotion recognition adds to the growing body of knowledge on the role of CACNA1C in cognitive functions affected in various psychiatric disorders." (PMID 26611642, 2015). "We investigated the influence of CACNA1C, a strong candidate gene for psychiatric disorders, on facial emotion recognition in healthy individuals to test its effect at the level of this intermediate phenotype." (PMID 26611642, 2015). "In this perspective, L-type calcium channels could be adequate drug targets in CACNA1C-related neurological and psychiatric disorders." (PMID 38790536, 2024). "In addition, we took the opportunity of interrogating two additional genes (CACNA1C and TCF4) widely implicated in major psychiatric disorders that were also included in the targeted panel." (PMID 35590255, 2022). "The CACNA1C gene is one of the most promising candidate genes for psychiatric disorders." (PMID 26611642, 2015). "However, our data provide clear support that CACNA1C has a subtle but functionally relevant influence on facial emotion recognition as an intermediate phenotype involved in psychiatric disorders." (PMID 26611642, 2015). "All these studies provide genetic evidence that CACNA1C may play a role in the etiology of psychiatric disorders." (PMID 26204268, 2015). "Dysregulation of cellular calcium homeostasis might be involved in ASD pathogenesis, and genes coding for the L-type calcium channel subunits CaV1.2 (CACNA1C) and CaVβ2 (CACNB2) were recently identified as risk loci for psychiatric diseases." (PMID 24752249, 2014). "SNPs in Ca channel (CACNA1C and CACNB2) genes have been identified as a susceptibility factor for bipolar disorder, schizophrenia and major depression, suggesting that altered functional expression of voltage-gated Ca channels is an important shared factor in psychiatric disorders." (PMID 33375447, 2020).
psychiatric disorder (continued). "The Genomic data suggested that CACNA1S, CACNA1C and CACNA1D were the core genes that related with psychiatric diseases." (PMID 38773596, 2024). "Four loci located close to genes ITIH3, AS3MT, CACNA1C, and CACNB2 reached genome-wide significance in meta-analysis of five major psychiatric disorders (SCZ, BD, ASD, ADHD, and depression) in the PGC study with the same direction of effects for these diseases." (PMID 29191242, 2017). "Moreover, here we show that miR-708-5p levels are elevated in Cacna1c+/− rats, a well-established genetic model of psychiatric disorders, even without environmental stressors." (PMID 40065182, 2025). "CACNA1C is reported to reach peak brain expression in late fetal/early childhood development and its forebrain deletion in embryonic, but not adult, mice models endophenotypes of psychiatric disorders." (PMID 33965196, 2021).
cancer (28 papers, 2008 to 2026). A tumor composed of atypical neoplastic, often pleomorphic cells that invade other tissues. "The expression of CACNA1H and ORAI1 was downregulated in KRAS-mutated cells, whereas CACNA1C was upregulated in all tested cancer cells." (PMID 35267511, 2022). "We combined TCGA and GTEx datasets to investigate the different expression levels of CACNA1C between pan-cancers and adjacent normal tissues." (PMID 34210324, 2021). "Additionally, seven proteins: Cacna1c, Vcl, Fcgbp, Mmp19, Lyz2, Eef1a1, and Gapdhs had cancer-only peptides." (PMID 19936259, 2009). "All of these indicated that CACNA1C could be served as a prognostic biomarker for human cancers." (PMID 34210324, 2021). "Our findings provide actionable targets (CACNA1C, CALM1, ACE, and LTA4H) for drug repurposing trials and underscore the clinical importance of personalized antihypertensive therapy in cancer prevention." (PMID 40535814, 2025). "Immunohistochemistry results indicated significant upregulation of GALP, CACNA1C, COL16A1, PENK, C4BPA, PSMA2, and CXCL9 in cancer tissues." (PMID 38481252, 2024). "Among the most significantly upregulated genes, we identified common biomarkers in human cancers: STC2, CACNA1C, and GAGE2A." (PMID 38493239, 2024). "Immunohistochemistry results indicated significantly elevated GALP, CACNA1C, COL16A1, PENK, C4BPA, PSMA2, and CXCL9 expression in cancer tissues." (PMID 38481252, 2024). "The significance of such enrichment reaches p < 10−58 for CACNA1C and SNX29 from the Network of Cancer Genes, and p < 10−61 for WWOX and CSMD1 from the Tumor Suppressor Gene Database." (PMID 33741065, 2021). "We found that the targets of nifedipine, such as voltage-dependent L-type calcium channel subunit alpha-1C (CACNA1C), subunit alpha-1D (CACNA1D) and beta-2 (CACNB2), have important links to cancer development and progression." (PMID 33893730, 2021). "The observation of overexpression of CACNA1A, CACNA1C, and CACNA1D could make them likely targets in cancer treatment, as it suggests that blockage or partial inhibition of their expression could help to modulate the status of metastatic diseases." (PMID 26147197, 2015).
tumor (20 papers, 2010 to 2026). "By combining these gene sets, we identified the leading genes that were associated with the tumor laterality: CACNA1C, CACNA2D2, CACNB2, KCNJ11, SCN3A, and SCN3B, signature that we called: 6-ICH signature." (PMID 37446299, 2023). "The orthotopic murine GBM model showed that CACNA1C overexpression rescued the tumor growth inhibition caused by 204-3p overexpression and significantly shortened the survival period." (PMID 36810326, 2023). "For instance, CaV1.2 encoded by the human CACNA1C gene is predominantly expressed in oesophageal squamous cell carcinoma and is correlated with tumour cell differentiation." (PMID 32575381, 2020). "CACNA1C has been confirmed to be associated with tumor metastasis and invasion." (PMID 41573567, 2025). "Our findings demonstrate that CACNA1C is a viable diagnostic marker for HGSOC and that its blockade with CCBs reduces tumor progression, highlighting their therapeutic potential." (PMID 42079127, 2026). "Meanwhile, SHROOM4 was found to co-express with PTPN13/CACNA1C impacting the tumor microenvironment (TME) and to participate in critical signaling pathways like cell circle and WNT." (PMID 41573567, 2025). "CACNA1C had a lower expression in OC tumor tissues than in normal tissues (P < 0.001), with significant OS (P = 0.013) and a low diagnostic efficiency." (PMID 34210324, 2021). "Our results indicated that CACNA1C had a lower expression in OC tumor tissues than in normal tissues, with significant OS and a low diagnostic efficiency." (PMID 34210324, 2021). "As for tumor microenvironment, the CACNA1C expression was markedly related to ESTIMATEScore and StromalScore (both P < 0.001)." (PMID 34210324, 2021). "In particular, over 29% of patient samples in the Breast Invasive Carcinoma24 data set displayed alterations in CACNA1C, CACNA1D, CACNA1F or CACNA1S and these alterations showed a significant association with unfavourable patient survival." (PMID 27910855, 2016). "miR-204-3p inhibits tumor proliferation through the CACNA1C/MAPK pathway." (PMID 36810326, 2023). "High expression of CACNA1C was associated with low survival in patients with OC and was independent of some clinical characteristics such as patient age, pathological grade, FIGO stage, tumor location, and venous infiltration." (PMID 37240946, 2023). "Obviously, CACNA1C was also lowly expressed in OC tumor tissues compared with normal tissues." (PMID 34210324, 2021). "Moreover, qRT-PCR results verified that the expression levels of CACNA1C were significantly down-regulated in the OC tissues compared with normal tissues (Normal = 6; Tumor = 6; P < 0.001)." (PMID 34210324, 2021). "For the four newly discovered tumor suppressor genes, i.e., KCNIP4, CACNA1C, PACRG, and ST6GALNAC3, previous studies have proved their regulatory effect in tumors." (PMID 35321246, 2022). "Transcriptome and survival analyses revealed four potential tumor suppressor genes including KCNIP4, CACNA1C, PACRG, and ST6GALNAC3." (PMID 35321246, 2022). "In contrast to humans, CACNA1C expression was much greater than CACNA1D in both feline tumor and nontumor adrenal tissue." (PMID 39429164, 2024). "VCGG channels, including CACNA1C, CACNA1D, CACNA1F, CACNA1E, CACNA1A, CACNA1G, CACNA1I, showed significantly higher expression in KIRC than normal cases, whereas CACNA1S and CACNA1H showed higher expression in normal than tumor cases." (PMID 36588677, 2022). "CACNA1C immunostaining was focally positive in tumor samples while negative in adjacent non-tumor mucosa." (PMID 34563241, 2021).
neurodevelopmental disorder (18 papers, 2013 to 2025). A behavioral and cognitive disorder with onset during the developmental period that involves impaired or aberrant development of intellectual, motor, or social functions. "CACNA1C pathogenic variants are associated with several phenotypes, including neurodevelopmental disorder with hypotonia, language delay, and skeletal defects with or without seizures." (PMID 41311988, 2025). "Therefore, this study aimed to explore the molecular mechanisms of three CACNA1C variants in causing neurodevelopmental disorders." (PMID 37448958, 2023). "Clinical characteristics of three patients with CACNA1C-related neurodevelopmental disorders in this study." (PMID 37448958, 2023). "Both mitochondria and lysosomes are involved in the pathogenesis of CACNA1C-related neurodevelopmental disorders." (PMID 37448958, 2023). "We performed several experiments in Human Embryonic Kidney 293 (HEK 293) and Chinese Hamster Ovary (CHO) to explore the role of mitochondria and lysosomes in the pathogenesis of the CACNA1C-related neurodevelopmental disorders." (PMID 37448958, 2023). "Recent human genetic studies have linked a variety of genetic variants in the CACNA1C and CACNA1D genes to neuropsychiatric and neurodevelopmental disorders." (PMID 36803254, 2023). "Among the gene families implicated in neurodevelopmental disorders, voltage-gated calcium channel genes—including CACNA1A (encoding Cav2.1), CACNA1C (Cav1.2), and CACNA1H (Cav3.2)—are of particular interest due to their central roles in neuronal signaling, excitability, and neurodevelopment." (PMID 40725423, 2025). "Our novel findings may assist in understanding the molecular mechanisms of CACNA1C-related neurodevelopmental disorders, and pave the way for the identification of potential treatment targets." (PMID 37448958, 2023). "A few studies provide some clues that mitochondria might play a role in the occurrence of CACNA1C-related neurodevelopmental disorders." (PMID 37448958, 2023). "Currently, most of the available molecular studies on CACNA1C variants were based more on the heart-related conditions rather than neurodevelopmental disorders." (PMID 37448958, 2023). "Nevertheless, the same Cav1.2 channel gating changes usually do not correlate with CACNA1C-related neurodevelopmental disorders." (PMID 37448958, 2023).
heart diseases (17 papers, 2016 to 2026). "The proband’s brother (IV-2) and sister (IV-3) carry the CACNA1C variant, increasing their risk of heart disease due to family history." (PMID 41287789, 2025). "Polymorphisms and mutations in the CACNA1C gene are associated with both psychiatric and cardiac disease." (PMID 37372947, 2023). "CACNA1C pathogenic variants cause a range of cardiac diseases that can be dichotomized by gain‐of‐function versus loss‐of‐function mutations." (PMID 33797204, 2021). "Mutations and polymorphisms of CACNA1C are implicated in neuropsychiatric and cardiac diseases." (PMID 39769475, 2024). "The results imply that alterations in CACNA1C per se can predispose to alterations in both behavior and cardiac function, providing a potential molecular link between neuropsychiatric disorders and cardiac disease." (PMID 37372947, 2023). "This Ca2+ handling remodeling in Cacna1c+/− rats under basal conditions may alter the heart’s response to stressors and thus cause an increased susceptibility to cardiac disease under conditions of mechanical or mental stress." (PMID 37372947, 2023). "Significantly, we found that EGT treatment downregulated intestinal Cacna1c expression and substantially reduced the abundance of the pathobiont Candidatus_Soleaferrea, a microorganism clinically associated with intestinal inflammation, cardiac diseases, and postoperative delirium." (PMID 41530565, 2026). "Therefore, we speculate that this kind of remodeling of cellular Ca2+ handling may increase the susceptibility of Cacna1c+/− rats to the development of cardiac disease during periods of physical or psychological stress." (PMID 39769475, 2024). "Thus, there is ample evidence that altered expression and function of CACNA1C/Cav1.2 is involved in psychiatric and cardiac disease and that the two entities might be linked." (PMID 37372947, 2023). "Some features of this Ca2+ handling remodeling in Cacna1c+/− myocytes are reminiscent of the remodeling observed in other cardiac diseases." (PMID 37372947, 2023). "Haploinsufficient Cacna1c+/− rats have proven to be a unique animal model exhibiting both a behavioral and a cardiac phenotype, thus enabling studies of the potential role of CACNA1C/Cav1.2 in neuropsychiatric and cardiac diseases." (PMID 39769475, 2024). "Altogether, targeting splicing factors of CACNA1C may provide alternative ways to prevent or even treat cardiac diseases." (PMID 29186814, 2017). "Thus, alterations in CACNA1C/Cav1.2 may constitute a molecular link between neuropsychiatric disorders and cardiac disease." (PMID 37372947, 2023).